SURF4 (surfeit 4)
Diseases named in the same sentence as SURF4 in open-access papers (continued):
Sharing a sentence is not in itself a finding about the gene and the disease.
mastitis (1 paper, 2024). Inflammation of breast tissue during lactation or postpartum due to an obstructed duct or infection. "The targeted genes, PLIN3, EDEM2, SURF4, and LGALS9, with mutations/variations have led to metabolic diseases, bovine osteoporosis, mastitis resistance and bovine respiratory disease, respectively." (PMID 38674383, 2024). "Additionally, the targeted genes like SURF4 and EDME2 of fs-cb-miRs are associated with mastitis and bovine osteoporosis, respectively." (PMID 38674383, 2024).
microcephaly (1 paper, 2026). A congenital or acquired developmental disorder in which the circumference of the head is smaller than normal for the person's age and sex. "Our findings suggest that YIPF5 and SURF4 coordinate ER export of key proteins and disruption may underlie cortical development defects leading to microcephaly." (PMID 41717013, 2026).
neuroblastoma (1 paper, 2023). Neuroblastoma (NB) is the most common solid, extracranial childhood tumor. "We found a lower Aβ toxicity when human neuroblastoma cells were transfected with SURF4 siRNA and an increase in cell toxicity when SURF4 was overexpressed." (PMID 36674792, 2023). "An in vitro analysis using human neuroblastoma cells showed that SURF4 silencing induced higher intracellular calcium levels, while its overexpression decreased calcium entry." (PMID 36674792, 2023). "To elucidate the effect of SURF4 in SOCE, we transfected human neuroblastoma cells with either a selective siRNA for silencing SURF4 or a plasmid to express SURF4, which resulted in a significant decrease or increase in mRNA SURF4 expression, respectively." (PMID 36674792, 2023).
Thrombocytopenia (1 paper, 2024). A reduction in the number of circulating thrombocytes. "In contrast with mice with hepatocyte-specific Lman1 deletion, mice with deletion of Surf4 in hepatocytes did not exhibit thrombocytopenia, suggesting that SURF4, unlike LMAN1, does not play a role in the secretion of TPO under steady-state conditions." (PMID 39499573, 2024). "Deletion of Surf4 in hepatocytes does not result in thrombocytopenia." (PMID 39499573, 2024).
cancer (4 papers, 2022 to 2023). A tumor composed of atypical neoplastic, often pleomorphic cells that invade other tissues. "Surf4 is highly expressed in human cancer tissues, and patients with higher Surf4 levels have shorter overall survival." (PMID 36574593, 2023). "Thus, downregulating the SURF4-mediated secretion of these secretory proteins provides a therapeutic strategy for cancer treatment." (PMID 36370847, 2022). "The expressions of SURF4 in different cancers were further studied using TIMER database." (PMID 36446386, 2022).
tumor (4 papers, 2022 to 2025). "In locales of elevated tumor cell density, surfeit locus protein 4 (SURF4) and the lipid metabolic gene lysophospholipase I (LYPLA1) have been corroborated as biomarkers inversely related to favorable outcomes." (PMID 39439806, 2024). "Consistently, overexpression of Surf4 increased cell proliferation and migration in vitro, and introduction of Surf4-overexpressing NIH3T3 cells into mice induced tumor growth." (PMID 36574593, 2023). "Our results indicated that SURF4 was significantly (P < 0.001) highly expressed in tumor." (PMID 36446386, 2022). "SURF4 is significantly (P < 0.001) highly expressed in tumor." (PMID 36446386, 2022). "SURF4 expression was significantly higher in tumor than adjacent normal tissue (P < 0.001)." (PMID 36446386, 2022). "Compared with normal tissue, SURF4 is significantly (P < 0.001) highly expressed in tumor." (PMID 36446386, 2022). "We confirmed SURF4-STING interaction in T cells and demonstrated that SURF4 downregulation activates T cell STING axis and downstream anti-tumor immunity." (PMID 40846839, 2025). "Conversely, SURF4 overexpression in T cells significantly reduced the expression of activation markers (CD3D, CD69) and anti-tumor proteins (GZMB), while simultaneously suppressing the p-STING/p-IRF3 axis." (PMID 40846839, 2025). "In conclusion, this study reveals the crucial role of NAD+ metabolism in regulating T cell function, with NAD+ increase promoting SURF4 ubiquitination and degradation, thereby stabilizing STING at the Golgi and enhancing T cell anti-tumor effects." (PMID 40846839, 2025). "This downregulation of SURF4 enables STING protein retention at the Golgi apparatus, subsequently activating the downstream p-IRF3 axis and interferon signaling, ultimately enhancing T cell-mediated anti-tumor immunity." (PMID 40846839, 2025). "First, the patients were divided into the low and high SURF4 expression groups according to the cut-off value between normal and tumor obtained from ROC curves." (PMID 36446386, 2022).
metabolic disorders (3 papers, 2023 to 2025). "Based on previous studies and our current findings, we propose that intestinal SURF4 plays a critical role in female-specific metabolic disorders, particularly in PCOS and its associated hyperandrogenic state." (PMID 41041130, 2025). "Downregulation of ANG, VEGFA, SURF4, and NIPA1 suggests impacts on neurodegenerative diseases and metabolic disorders." (PMID 38681774, 2023).
infection (2 papers, 2021 to 2023). The state of being infected such as from the introduction of a foreign agent such as serum, vaccine, antigenic substance or organism. "LAMP2 or SURF4 were also up-regulated in ECFCs in response to the serum of critical patients as well as in ECFCs with PCR+ serum (at the highest peak of infection) and, interestingly, in individuals that had overcome the infection without apparent symptoms (PCR-/IgG+)." (PMID 37063416, 2023). "However, siRNA knockdown of SURF4 decreased the viral RNA levels and the number of infectious particles released during infection with the attenuated VEEV-TC-83 strain." (PMID 33788849, 2021). "In addition, the analysis revealed that some of these proteins had been previously associated to SARS-CoV-2 early (FKBP2; UBXN1; PPP1R11), middle (UBXN1; PPP1R11; CAPN5) and late-stage infection in human male blood (FKBP2; UBXN1; PPP1R11; SURF4; SSU72)." (PMID 37063416, 2023). "Interestingly, depletion of SURF4, an ER cargo receptor, increased virulent VEEV-TrD infection, suggesting an antiviral effect in agreement with the prediction based on the viscRNA-Seq data." (PMID 33788849, 2021).
cardiovascular disease (1 paper, 2022). "Furthermore, polymorphism and mild reduction of SURF4 expression strongly associate with lower plasma lipid levels and reduced risks of cardiovascular disease in human populations." (PMID 36193893, 2022).
neurodegenerative disease (1 paper, 2023). A disorder of the central nervous system characterized by gradual and progressive loss of neural tissue and neurologic function. "SURF4 affects insulin secretion, and reductions in NIPA1 are tied to neurodegenerative diseases." (PMID 38681774, 2023).
SURF4 also shares sentences with these, for which no sentence is quoted: Chagas disease (1 paper); COVID-19 (1); dyslipidemia (1); Hepatitis (1); Hepatitis C (1); hereditary angioneurotic edema (1); hyperprolinemia type 2 (1); liver cancer (1); lymph node metastasis (1); malaria (1); myeloid leukemia (1); osteoporosis (1); polycystic ovary syndrome (1); primary immunodeficiency (1); schistosomiasis (1); triple-negative breast carcinoma (1).